CD4 (CD4 molecule)
Diseases named in the same sentence as CD4 in open-access papers (continued):
Sharing a sentence is not in itself a finding about the gene and the disease.
infection (continued). "In particular, they examined the expression of granzyme B, perforin, and IFNγ in CD4+ T cells from the lung and in draining mediastinal lymph nodes, showing the presence of cytolytic effector cells only at the site of infection, as further confirmed by the upregulation of CD107a in the same cells." (PMID 28289418, 2017). "GS-9620 was inactive against HIV in isolated CD4+ T cells and macrophages up to the highest concentration tested (10 μM) but did show dose-dependent inhibition of HIV-1 replication in complete PBMCs following infection with either HIV-1BaL (EC50 = 536 nM) or HIV-1VSV-G-LUC (EC50 = 953 nM)." (PMID 27799218, 2017). "When the mice were analyzed on day 11 post-infection, EYFP expression in CD11c-positive B220+ plasmablasts was detected in wild-type recipient mice, but not MHC II-deficient mice, indicating that CD4 T cells were required for Aicda expression." (PMID 28575114, 2017). "In our study, we also show that stabilization of specific T-cell phenotypes occurs months after viremia or CD4 count stabilize in the course of infection, adding more evidence to the arguments for treatment initiation regardless of CD4 counts or viremia levels." (PMID 29354131, 2017). "IL-18R, but not IL-1R, is upregulated in CD4+T cells upon activation following infection." (PMID 28895840, 2017). "Thus, CD4+ T cell-dependent myeloid infection control could have reflected either that only CD4+ T cells efficiently recognized infected myeloid cells (via MHC II), or that only IFNγ was able to control their infection." (PMID 28394921, 2017). "Anti-retroviral therapy (ART) provided to HIV-1-infected patients infected with human immunodeficiency virus type 1 (HIV-1) does not lead to virus eradication as HIV-1 persists in memory CD4+ T cells which represent a stable and long-lived reservoir for this infection." (PMID 29375579, 2017). "Moreover, the infection promoted the expansion of the CD4+ IL-17+ gated on CD3+ cells, but such population was not affected in the absence of the receptor." (PMID 28775724, 2017). "However, there was a great variation in values among CD4+ T cells, indicating that some subjects develop HCMV-specific CD4+ T cells with an IL-7Rpos phenotype early after infection, whereas other subjects maintain a high frequency of IL-7Rneg HCMV-specific CD4+ T cells for long periods of time." (PMID 29112951, 2017). "FDCs also adhere HIV virions through their highly expressed complement receptors CR1 and CR2 or the DC-specific, ICAM-3 grabbing non-integrin (DC-SIGN) and retain infectious virus within non-degradative cycling endosomes, allowing the infection of uninfected CD4+ T cells." (PMID 29085360, 2017). "On the other hand, subsequent studies clearly demonstrated that high levels of HIV-1 Gag-specific CD4+ CTL could be detected in long-term non-progressors successfully controlling their infection." (PMID 28289418, 2017). "This lack of significant CD4+ T cell expansion may be the consequence of a slowly controlled infection, or even a lack of control due to serial infections." (PMID 28662714, 2017). "However, the average percentage of CD4+ T cells in SLE patients with infection was significantly lower than that in SLE patients without infection (32.1 vs 40.2%, P=0.001)." (PMID 29267496, 2017). "The results demonstrated that the infection with the oncogenic virus does not increase the frequencies of TGF-beta Treg cells in the MDV resistant chicken line (TGF-beta Treg cells as % of CD4 T cells were 1.95± 0.54 in the infected chickens compared to %1.86± 0.47 in the control group)." (PMID 29267390, 2017). "Therefore, CD30 is dispensable for CD4 and CD8 T-cell responses in chronic LCMV clone 13 infection." (PMID 28993768, 2017).
infection (continued). "Eight days postinfection, an increase in T-bet– and IFN-γ–expressing CD4 T cells was detected in CD2-specific Egr2/3−/− mice, suggesting that the high levels of T-bet–expressing T cells in CD2-specific Egr2/3−/− mice result from hyperactivation of T cells at late stages of infection." (PMID 28455436, 2017). "Thus, our results indicate that maintaining Th1-biased CD4 T cell responses may prevent CD8 T cell exhaustion and viral persistence early during Cl-13 infection allowing for more rapid viral control." (PMID 28715493, 2017). "To date, the CD4+ T cell-intrinsic pathways altered by transmitted/founder (TF) HIV-1, which best approximate the initial strains, i.e. those identified to have established clinical infection in vivo, remain unknown." (PMID 28241075, 2017). "The non-pathogenic nature of gp41 mutant V38E was not limited to in vitro studies but was also observed in humanized mice, where infection with V38E mutant resulted in slower CD4 decline accompanied with a lack of bystander apoptosis compared to infection with wild type virus." (PMID 28829402, 2017). "We cannot exclude that lack of correlation between pools of Mtb-specific CD4+ cells and TB severity may result from the preferential accumulation of antigen-specific cells at the site of infection." (PMID 28871253, 2017). "In summary, our results indicate (i) that CD4 immunodominance hierarchy during blood stage is dictated in part by the route of challenge and by the duration of blood‐stage infection and (ii) that ETRAMP ultimately establishes as a prominent blood‐stage peptide after both spz and pRBC infections." (PMID 28935714, 2017). "The early IL-4 response to L. major is confined to CD4+ T cells expressing a Vβ4+Vα8+ T cell receptor that recognizes the Leishmania antigen LACK (Leishmania homolog of receptors for activated C kinase), in addition to mast cells and eosinophils at the site of infection and draining LN." (PMID 29176972, 2017). "Moreover, we found that contrary to IL-18R, IL-1R is not expressed on CD4+ T cells in response to infection with T. cruzi." (PMID 28895840, 2017). "Thus, CD8+ T cells appeared to be more important than CD4+ T cells for acute infection control because they targeted a more immediately virus-productive cell type—AEC1—while a lack of CD4+ T cells increased AM infection." (PMID 28394921, 2017). "Using a mixed design repeated measures ANOVA analysis, a significant mean difference in CD4 count over time (F = 16.347, df = 1.328, 1005.422; p<0.001) was observed among all the subjects enrolled in this study irrespective of the infection status (single or dual)." (PMID 28346490, 2017). "The proliferation of 2W+ CD4+ T cell populations in groups I and III mice was comparable following peptide stimulation in vivo indicating that an effector response could also result in mice with low-dose asymptomatic infection." (PMID 29312315, 2017). "The reporter cell line TZM-bl, expresses CD4, CXCR4 and CCR5 receptors; thus, its expression of these receptors is similar to that on the HIV-1 target cell, CD4+ T cell, and is suitable for evaluating infection by R5, R4, or dual R5 and R4 HIV-1 viruses (SF162, R5; DH12, dual R5 and R4)." (PMID 29226013, 2017). "Off-target effects increase the migratory challenge for affecting infected CD4+ T-cells with minimal influence on bystander cells using strategic drug therapies for migration in and out of target-rich niches without producing new infections." (PMID 28462923, 2017). "CD4 T cell help was not required for the generation of IgM bone marrow ASCs in our experimental model, because the ASCs were detected in both wild-type and MHC class II-deficient mice on day 30 post-infection." (PMID 28575114, 2017). "No HIV could be detected from CSF, bone marrow cells or CD4+ T cell subsets from a whole excised inguinal lymph node 8–9 months following infection." (PMID 29112956, 2017). "This suggests that CD4+ T cells are not a main source of TNF-α during APP infection." (PMID 28166835, 2017).
infection (continued). "Multiparameter flow cytometry confirmed that polyfunctional T. cruzi-responsive T cells in SD subjects are enriched in highly competent IL-2-producing T. cruzi-specific CD4+ T cells, consistent with exposure to T. cruzi but the absence of a long-term active infection." (PMID 28966620, 2017). "However, despite expansion of CD4+ T cells and increased IFNγ expression in the spleen, humans with active VL do not control the infection." (PMID 28103263, 2017). "As seen for CD8+ T cells the absolute cell counts of CD4+ T cells did not increase during the course of infection but the frequency of CD4+ T cells that expressed intracellular IFNγ was significantly increased on day 7 post infection (8.54±0.60% compared to 5.66±0.27% in control mice (day 0))." (PMID 28222146, 2017). "CD4+ T cells but not ILC2 expressed detectable amounts of IL-13 at this stage of infection." (PMID 29045902, 2017). "However, neither CD4+ nor CD8+ T cells were detected during the whole period of infection and neither were lymphocytes." (PMID 28038465, 2017). "Interestingly, eSF also enhanced infection of unstimulated CD4+ T cells, although never in the same range as for activated cells." (PMID 28207890, 2017). "Unlike SHIV-KS661 infection, the reduced CD4+ T-cell depletion observed in SHIV-#64 infection might lead to better T-cell dependent help for both antibody and CD8+ T-cell responses to the virus." (PMID 28431573, 2017). "However, about 11% of the patients from SA also showed a positive serology for previous helminth exposure/infection with helminth but no sign of generation of Mtb-specific Th2 CD4 T cells." (PMID 28759590, 2017). "We did not observe a significant decline in human CD4+ cells at the time of infection." (PMID 29084769, 2017). "Additionally, the IDR (p < 0.0001, R = −0.7815) and the frequencies of multifunctional CD4+ (p < 0.0500, R = −0.2803) and CD8+ T cells (p < 0.0001, R = −0.7837) expressing IL-2, TNF-α, and IFN-γ, after infection, were strong correlates of prophylactic efficacy." (PMID 28280494, 2017). "Resting CD4+ T cells are thought to serve as latent reservoirs of HIV and SIV during ART treatment, and some latency reversal agents have produced successful reactivation of those reservoirs in attempt to eliminate the infection with continued long-term ART treatment." (PMID 29259605, 2017). "The infection stage of the other eight patients remained unknown due to the absence of information in the literature regarding CD4-positive cell count and stage 3-defining opportunistic diseases." (PMID 28490364, 2017). "Splenic CD4+ T cell and CD8+ T cell activation was, however, largely unaltered, as determined by comparing the levels of granzyme B, KLRG-1, and Ki-67 expression in IFN-γR−/− mice to the levels in VAV-Cre+ IFN-γR2flox/flox mice and WT mice on day 7 of infection." (PMID 28874445, 2017). "As previously observed, analysis of thymic differentiation of DN, DP and SPs thymocytes regarding CD4 and CD8 markers during the acute infection, showed a huge decrease in the percentages and total numbers of DP thymocytes, starting at 13 d.p.i. and partially recovering later in infection." (PMID 28147332, 2017). "We saw a rapid increase in neutralizing antibodies after FV challenge infection which was probably assisted by the vaccine-induced CD4+ T cells, but it has to be assumed that the lack of potent neutralization prior to FV challenge infection prevents complete protection." (PMID 28166802, 2017). "Thus, the accumulation of CD38+ CD4+ T cells in the peripheral blood upon infection is not due to the recruitment of CD38- CD4+ T cell subsets into other body compartments such as lymphoid organs." (PMID 27662621, 2016). "Furthermore, our results demonstrate that pDCs neither promote nor regulate hepatic CD4+ T cell responses at this stage of infection." (PMID 26657145, 2016).
infection (continued). "The antiviral effect of BIT225 increased over time following MDDC infection, such that increased exposure to BIT225 resulted in a decreased virus burden within the MDDC, leading to a reduction in HIV-1 transfer to the more permissive CD4+ T cell (DMSO v BIT225 at Day 12, n = 2, p = 0.12)." (PMID 26858771, 2016). "Thus, the majority of HIVinfected individuals are likely starting ART late in infection, regardless of agiven CD4-based guideline." (PMID 29492277, 2016). "As compared to CD4-Cre-IL-10flox/flox (Cre-) control mice, Cre+ mice mounted elevated CD4+/IFNγ+ responses in the salivary glands to multiple MCMV antigens throughout the course of infection, most notably M25- and m142-specific cells at d14 pi when peak IL-10+ responses were observed in Cre- mice." (PMID 27926930, 2016). "Similar to infected PBMC cultures, R3A-5/6AA replication was delayed initially at 1 week post infection but reached similar viremia levels as R3A at 2 and 3 weeks post infection as measured by HIV genomic RNA levels in the blood and intracellular p24 staining of CD4 T cells in the spleen." (PMID 27026376, 2016). "Thus, the enhanced IL-10 response during secondary infection is unlikely to be dominantly or solely controlled by the specific environment the CD4+ T cells are exposed to during rechallenge." (PMID 27630165, 2016). "In our patient, the ultimate mycobacterial blood culture results reported as negative; nevertheless, in light of her very low CD4 count, there is a very high possibility that the infection would have spread hematogenously, and intra-abdominal lymph nodes would have been certainly involved." (PMID 27803833, 2016). "Based on the frequency of infection of CD4+ T cells quantitated by the standard QVOA and the CD4+ T cell percentages in the blood and spleen determined by flow cytometry, we calculated that there was, on average, less than one infected CD4+ T cell in any of the Mφ-QVOAs." (PMID 27030272, 2016). "Our results show that IFN-γ from CD4 T cells accounts for ~30% of the total anti-bacterial effects of CD4 T cells in the lungs early in infection, and this relatively low contribution of IFN-γ is not explained by insufficient production of the cytokine by CD4 T cells." (PMID 27244558, 2016). "Thus, IAV-specific CD4 effectors were generated in vivo by isolating CD4+ cells from the lung and draining lymph node (DLN) at the peak of the response after sublethal PR8 infection and adoptively transferred into naïve hosts that were then given lethal doses of PR8." (PMID 27014272, 2016). "Therefore, we investigated whether DCs that underwent maturation following exposure to Rv3628 could specifically stimulate effector/memory CD4+ and CD8+ T cells isolated from the spleens of Mtb H37Rv-infected mice at 8 weeks post-infection." (PMID 27097115, 2016). "Direct infection of CD4+ T cells does not appear to result in pyroptosis." (PMID 27592079, 2016). "However, this approach might represent an oversimplification, as during the course of an infection, or an epidemic, HIV-1 populations face changes in viral load, CD4 count, and ART experience that occur simultaneously." (PMID 27907076, 2016). "Furthermore, bacterial load was determined at the time of death in control animals and CD4+ T cell recipients that did not survive the infection." (PMID 27875529, 2016). "However, IL-15 SA predominantly expands NK, NKT, and mCD8+ lymphocytes, whereas preferential expansion of naïve and effector CD4 and CD8 T-lymphocyte populations, with therapies such as IL-7, may provide more effective resistance to infection." (PMID 26859674, 2016). "However, death of non-infected bystander CD4 + T cells occurs by an abortive infection-induced-pyroptosis, an IL-1β driven inflammatory process, mediated by caspase-1 activation." (PMID 27211546, 2016).
infection (continued). "To determine the effect of NK cell depletion on the frequency of activated/effector memory CD4+ T cells following secondary IOE infection, we measured the expression of CD62L and CD44 on T cells in the spleen of NK-/-EM/IOE and NK+/+EM/IOE mice 7 DPI after IOE infection." (PMID 27092553, 2016). "However, Th1 cells (primarily CD4+ cells producing IFN-γ) alone are not capable of controlling the infection and other factors, including Th2 cells, Th17 cells and regulatory T cells (Treg cells), are also involved in the progression of MTB infection." (PMID 27311307, 2016). "Note that our model does not generate testable predictions regarding early infection dynamics, as it does not include biological features that are likely prominent in that phase, such as HIV-specific CTL accumulation, CD4+ T cell loss at the systemic level, and evolution of CTL escape." (PMID 27706164, 2016). "In our model for retroviral infection of the neonate, immunotherapy of the adult with nontolerized virus-specific CD4+ T cells cannot provide sterile immunity because infection affects the majority of the hematopoietic system, and every cell also carries germline copies of the precursor proviruses." (PMID 27647833, 2016). "Though a series of studies have shown that IFN-γ and CD4+ T cells play important roles in controlling both bacterial growth and immunopathology during MTB infection, the Th1 cells (primarily CD4+ cells producing IFN-γ) alone is not enough to control the infection." (PMID 27311307, 2016). "Additionally, the frequency of Ki67+ cells decreased at 7 days post infection compared to prior to infection in CD38+ but not in CD38- CD4+ T cells." (PMID 27662621, 2016). "However, both CD4+ and CD8+ T‐cell responses decreased in magnitude late after infection." (PMID 27631819, 2016). "Broadly directed CD4+ T cells may be present during initial HCV regardless of infection outcome, but CD4+ T cells become defective early in those that progress to chronic infection." (PMID 27362419, 2016). "Moreover, IFNAR1-mediated regulation of ICOS expression in CD4+ T cells was observed in both the Th1 and emerging Tfh compartments during PcAS infection; and IFNAR1-signalling also reduced ICOS+ Tfh cell numbers during Py17XNL infection." (PMID 27812214, 2016). "Administration of a single dose of a well characterised CD4+ cell depleting monoclonal antibody on day 0, 3 hours prior to infection, led to a complete absence of detectable CD4+ T cells in the lungs of both RV and PBS challenged Tbet-/- mice at 7 days post-challenge." (PMID 27683080, 2016). "Whilst T helper cells could obviously not be measured in antibody treated mice, an absence of induction of Il4, Il13 and Il17a mRNAs in the lung following infection supported an absence of Th2 and Th17 responses in CD4+ cell depleted mice." (PMID 27683080, 2016). "Furthermore, B cell-deficient μMT mice infected with LCMV were shown to have no defect in CD4+ T cell expression of Bcl6 or CXCR5 at day 3 post-infection, suggesting that B cells are not exclusively responsible for promoting early Tfh cell induction." (PMID 27559335, 2016). "Such a mechanism of viral transcytosis is reminiscent of previous work showing transcytosis of HIV across an epithelial barrier, without infection of enterocytes, and subsequent infection of macrophages or CD4 lymphocytes located to the basal side of the epithelium." (PMID 26848683, 2016). "In contrast, CD4 T-cell counts before infection had no impact on the rate of progression." (PMID 27509048, 2016). "Thus, circulating CD38+ CD4+ T cells that expand during infection do not represent a specific subset of Tfh cells." (PMID 27662621, 2016). "This was an unexpected result, given that, although on the order of 1,000/106 resting CD4+ T-cells harbor an HIV provirus in a typical ARV-treated subject, only in the range of 1/106 of these harbor an intact inducible virus that can re-seed infection in viral outgrowth assays." (PMID 27082643, 2016).